LURAP1 (leucine rich adaptor protein 1)
Description:
Acts as an activator of the canonical NF-kappa-B pathway and drive the production of pro-inflammatory cytokines. Promotes the antigen (Ag)-presenting and priming function of dendritic cells via the canonical NF-kappa-B pathway. In concert with MYO18A and CDC42BPA/CDC42BPB, is involved in modulating lamellar actomyosin retrograde flow that is crucial to cell protrusion and migration. Activates CDC42BPA/CDC42BPB and targets it to actomyosin through its interaction with MYO18A, leading to MYL9/MLC2 phosphorylation and MYH9/MYH10-dependent actomyosin assembly in the lamella (By similarity).
Synonyms: C1orf190; LRAP35A; LRP35A; FLJ25163
Tractability: No criterion of Open Targets' tractability assessment is met for any kind of drug.
Gene: Protein-coding gene on chromosome 1 (46,203,334 to 46,221,256, forward strand). Ensembl gene ENSG00000171357.
Subcellular location: Cytoplasm
Subcellular location (Human Protein Atlas): Cytosol; Vesicles
Gene Ontology:
Molecular function: protein binding
Biological process: positive regulation of canonical NF-kappaB signal transduction; positive regulation of cytokine production
Cellular component: cytoplasm; cytosol
Genetic constraint (gnomAD): Loss-of-function variants: 14 observed, 19.33 expected, observed/expected ratio (o/e) 0.72, 90% interval 0.48 to 1.13. The upper end of that interval is the gene's LOEUF score, 1.13, which puts it in group 4 of 6, group 1 being the genes least tolerant of losing a copy. Missense variants: 273 observed, 306.67 expected, observed/expected ratio (o/e) 0.89, 90% interval 0.81 to 0.98. Synonymous variants: 129 observed, 128.81 expected, observed/expected ratio (o/e) 1, 90% interval 0.87 to 1.16.
Homologues: Orthologues: chimpanzee LURAP1 (99% identical), macaque LURAP1 (97% identical), pig LURAP1 (91% identical), dog LURAP1 (86% identical), rat Lurap1 (85% identical), rabbit LURAP1 (85% identical), mouse Lurap1 (84% identical), guinea pig LURAP1 (82% identical), zebrafish lurap1 (48% identical), tropical clawed frog lurap1 (46% identical). Paralogues in human: LURAP1L (31% identical).
Diseases named in the same sentence as LURAP1 in open-access papers:
LURAP1 is named in the same sentence as 5 diseases in open-access papers, as found by Europe PMC text mining. Sharing a sentence is not in itself a finding about the gene and the disease. The quoted sentences say what the papers report.
Obesity (2 papers, 2015 to 2016). Accumulation of substantial excess body fat. "LURAP1 (previously C1orf190) is an activator of the NF-κB signaling pathway which plays a crucial role in obesity-induced inflammation." (PMID 25938420, 2015). "Its paralog, LURAP1, was shown to play a crucial role in obesity-induced inflammation." (PMID 27930681, 2016).
bladder cancer (1 paper, 2025). "Notably, our finding that under expression of LURAP1 is associated with better response to atezolizumab is consistent with previous evidence from TCGA bladder cancer data, where hypermethylation of five CpG sites in LURAP1 (resulting in reduced expression) was linked to improved overall survival." (PMID 41357226, 2025).
developmental delay (1 paper, 2017). "This indicates that the CE defects were not caused by a developmental delay, and that maternal Lurap1 is specifically required for CE movements." (PMID 29116181, 2017).
cancer (1 paper, 2023). A tumor composed of atypical neoplastic, often pleomorphic cells that invade other tissues. "The remaining genes in the hyperloss category are ECHDC3, KRTCAP3, LURAP1, and MAMDC4, none of which are known drivers in cancer." (PMID 37245006, 2023).
LURAP1 also shares sentences with these, for which no sentence is quoted: tumor (1 paper).